RB1 (RB transcriptional corepressor 1)
Diseases named in the same sentence as RB1 in open-access papers (continued):
Sharing a sentence is not in itself a finding about the gene and the disease.
retinoblastoma (continued). "Less than 10% of patients with heritable retinoblastoma have large deletions that include the whole RB1 gene, and a complete absence of pRB expression is to be expected." (PMID 33807189, 2021). "Beyond the RB1 gene, amplification of the proto-oncogene MYCN has been reported in a small subset (~ 2%) of sporadic retinoblastoma cases without RB1 alterations." (PMID 33827698, 2021). "A small subset of patients who develop unilateral retinoblastoma have been found to have MYCN amplification and no RB1 alterations." (PMID 32633890, 2020). "As a result of this expanded understanding of RB1 and its role in heritable and non-heritable retinoblastoma, a new component (“H”) was incorporated into the 8th edition (2017) American Joint Committee on Cancer (AJCC) Cancer Staging Manual for retinoblastoma." (PMID 31683923, 2019).
breast cancer (462 papers, 2001 to 2025). A primary or metastatic malignant neoplasm involving the breast. "Our data corroborate this association in contemporary cohorts of breast cancer and OV for both RB1-defective patients and additional patients who exhibit RBness." (PMID 40138429, 2025). "In Rb1-deficient tumors—including CDK4/6i-resistant breast cancer—upregulation of mitosis-associated E2F target genes provides a therapeutic opportunity for AURKA inhibitors to trigger replication stress via synthetic lethality, leading to tumor cell death." (PMID 40949156, 2025). "To elucidate molecular drivers of RBness other than RB1 defects, we examined RBness cancers for the enrichment of mutations, amplifications, and deletions of known breast cancer driver genes." (PMID 40138429, 2025). "In RB1-deficient breast cancer models, CFI-402257 induces premature chromosome separation and excessive mitotic segregation, resulting in elevated DNA damage and enhanced genomic instability." (PMID 40949156, 2025). "RB1 knockout cells were used due to the prevalence of RB1 mutations in breast cancer conveying resistance to CDK4/6 inhibitors." (PMID 40650785, 2025). "RB1 is a cell cycle regulator, implicated in coordinating multiple pathways leading to the disease progression of ER+ breast cancer and is related to the CDK4/6 activity—RB dependency integrated signature." (PMID 39031010, 2024). "We also found RB1 mutations to be significantly depleted in B7-H3–high breast cancers that are hormone receptor (estrogen receptor/progesterone receptor) positive (HR+)/HER2 negative (1.6% vs. 8.7%, q < 0.0001)." (PMID 38709075, 2024). "Heterozygous RB1 loss was also recently reported as a biomarker for CDK4i/6i resistance in ER+ breast cancer." (PMID 38066089, 2024). "Since RB1 loss-of-function alterations confer resistance to CDK4/6i in ER+ metastatic breast cancer patients, a genome-wide CRISPR screen identified protein arginine methyltransferase 5 (PRMT5) as a vulnerability in ER+/RB1-deficient breast cancer cells." (PMID 38672640, 2024). "CDK4/6 inhibitors have improved outcomes for patients with ER+ breast cancer, however, those with loss of RB1 function often fail to respond." (PMID 38480701, 2024). "RB1 mutations and gene loss have been shown to induce resistance to Palbociclib in breast cancer cells." (PMID 37606819, 2024). "Inhibition of PRMT5 blocked the G1-to-S cell cycle transition in ER+/RBKO breast cancer cells and other cancer cells with natural loss-of-function alterations of RB1." (PMID 37502925, 2023). "Altogether, our results show that RB1 mutation is associated with RB1-L and mediates sensitivity to PARPis in lung cancer and breast cancer." (PMID 37937640, 2023). "For example, a study on breast cancer patient’s genomes showed a widespread loss of miR-3613-3p DNA fragment, located near the tumor suppressor genes RB1 and BRCA2 (13q13.1)." (PMID 35200555, 2022). "The potency of abemaciclib, palbociclib and ribociclib was investigated in a panel of 37 breast cancer cell lines presenting different molecular profiling status, including Rb1 deficiency, ER/AR expression, HER2 amplification, and PIK3CA or BRCA1/2 mutations." (PMID 35813283, 2022). "For example, mutations Leu607Ile, Arg698Trp, and Arg621Cys identified in breast cancer patients were shown to have impaired pro-apoptotic function of Rb1 and they stimulated resistance to 5-FU/mitomycin or doxorubicin." (PMID 35267571, 2022). "We also observed a loss of Rb1 activity, which has been associated with therapeutic resistance in ER+ breast cancers." (PMID 35671075, 2022).
breast cancer (continued). "It has been reported that in several lung cancer and breast cancer cell lines, loss of RB1 makes cells hyperdependent on AURKB for their survival." (PMID 35853811, 2022). "RB1 loss in breast cancer is associated with resistance to many therapies, including chemotherapy and radiation, and the presence of WT RB protein is an important determinant for the efficacy of CDK4/6 inhibitor monotherapy." (PMID 34932500, 2022). "The PALOMA-3 trial provided important clinical evidence regarding the involvement of acquired RB1 mutations in the emergence of resistance to palbociclib in advanced ER+ breast cancer." (PMID 35740538, 2022). "RB1 loss in breast cancer cells activates fatty acid oxidation (FAO) and induces following Jun kinase (JNK) activation." (PMID 34359636, 2021). "In keeping with these results, RB1-deficient breast cancer cell lines exhibited strongly diminished response to CDK4/6i treatment." (PMID 34508104, 2021). "In the present study, we first found a widespread loss of miR-3613-3p DNA fragment (13q14.2) in breast cancer patients genome, which located near the famous tumor suppressor genes RB1 (13q14.2) and BRCA2 (13q13.1)." (PMID 33494814, 2021). "A SKP2 inhibitor inhibited proliferation of RB1-deficient breast cancer cells more efficiently than in RB1-proficient cells, and did so in a dose-dependent manner, consistent with previous observations." (PMID 33591981, 2021). "This is consistent with the recent reports that RB1 loss in breast cancer induced mitochondrial protein translation and increased OXPHOS38." (PMID 32826891, 2020). "Breast cancer cell lines characterized by loss of RB1 activity are hyposensitive to CDK4/6 inhibitors; however, loss of RB1 function is rare in ER-positive breast cancer." (PMID 31448056, 2019). "The results on RB1 agree with other studies that reported the loss of RB to be correlated with advanced disease and often with ER- subtypes of breast cancer." (PMID 31781306, 2019). "In consistency with our results, other studies have shown that ATM/RB1 inactivation were associated with poor prognosis in multiple cancer types, such as leukemia, breast cancer, lung cancer, brain tumor and bladder cancer." (PMID 29682192, 2018). "In breast cancer, Rb1 deficiency or loss of its function results in palbociclib resistance, and the same has been shown for GBM." (PMID 28903422, 2017). "Consistent with this notion, CENPI mRNA levels are significantly elevated in breast cancers with RB1 loss (p<0.0001, Mann-Whitney U test)." (PMID 28977935, 2017). "Similar to breast cancer, also in prostate cancer RB1 deficiency seems to be associated with a poor response to hormone therapy (including surgical or chemical castration to suppress androgen production and/or administration of antiandrogens)." (PMID 26160835, 2015). "Conversely, RB1 pathway deregulation in breast cancers proved to be associated with resistance to hormone therapy with the antiestrogen tamoxifen and tumor recurrence." (PMID 26160835, 2015). "RB1 pathway disruption is associated with improved response to multiple chemotherapeutic regimens in both ER+ and ER− breast cancers." (PMID 26160835, 2015). "Loss-of-function of Rb or genetic ablation of RB1 has been implicated in advanced stages of brain cancers, prostate cancer, breast cancer, and lung cancer." (PMID 24919196, 2014).
breast cancer (continued). "Acute inactivation of RB1 in hormone-dependent luminal breast and colon cancer cells increases response to several antineoplastic drugs, suggesting that RB-deficiency affects therapeutic outcome in certain tumor types including ER+ breast cancer." (PMID 24265703, 2013). "Although rare, our findings suggest RB1 mutations to be of pathological importance potentially affecting sensitivity to mitomycin/anthracycline treatment in breast cancer." (PMID 20594292, 2010). "Further, in support of a pro-apoptotic role of the pRb protein in breast cancer, three out of four tumors harboring RB1 mutations expressed resistance to doxorubicin or mitomycin treatment in vivo." (PMID 20594292, 2010). "cDNA generated from 73 locally advanced breast cancer samples obtained prior to chemotherapy was analyzed by PCR and DNA sequencing for RB1 mutations." (PMID 20594292, 2010). "RB1 has been reported to be aberrant in approximately 20% of breast cancer cases, and to be associated with a poor disease outcome." (PMID 21203526, 2010). "We used gene expression analysis for tumour subtyping and polymorphic markers located at the RB1 locus to assess the frequency of loss of heterozygosity in 88 primary human breast carcinomas and their normal tissue genomic DNA samples." (PMID 18782450, 2008). "Subsequent studies have shown somatic mutation of RB1 in a variety of cancers, including sarcomas, breast cancer, lung cancer and genitourinary cancers." (PMID 16685266, 2006). "Additionally, impairing mutations or loss of the RB1 gene have been reported in breast cancer patients with poor responses to CDK4/6is." (PMID 40244377, 2025). "To identify cancers that phenocopy RB1 genomic defects (deleterious mutations or deletions), we integrated proteomic, transcriptomic, and genomic data from 1093 breast tumors described in The Cancer Genome Atlas’ (TCGA) breast cancer (BRCA) dataset." (PMID 40138429, 2025). "The role of ATM and RB1 in cell cycle control and cellular senescence, as well as their connection to trastuzumab resistance, offers important insights into the mechanisms underlying therapeutic resistance in breast cancer." (PMID 39655080, 2024). "In breast cancer, retinoblastoma 1 (RB1) mutations were highly prevalent." (PMID 37702806, 2023). "To investigate whether intact RB protein expression was necessary for radiosensitization in breast cancer cell lines, we first sought to determine how RB1 loss would affect the radiation response in breast cancer cell lines." (PMID 34932500, 2022). "Interestingly, different Rb1 mutations were identified as a result of the treatment of breast cancer patients with CDK inhibitors and were considered to confer therapeutic resistance." (PMID 35267571, 2022). "Chronic loss of Rb1 was found to be a cause of resistance to CDK4/6 inhibitors in breast cancer." (PMID 34123801, 2021). "However, while RB1 loss-of function mutation has been associated with adaptive resistance to CDK4/6 inhibitors in breast cancers, less is known about a potential effect of heterozygous RB1 copy number loss." (PMID 33947352, 2021). "Thus, further clinical evidence is needed to analyze the frequency of Rb1 mutation in breast cancer patients receiving CDK 4/6 treatment." (PMID 34123801, 2021). "Mutational loss of RB1 has been linked to the development of breast cancer." (PMID 33726790, 2021). "Furthermore, oxidative phosphorylation is significantly upregulated in breast cancers deficient in RB1, a protein lost in 20–30% of basal-like breast cancers." (PMID 32694701, 2020).
breast cancer (continued). "Consistently, it is overexpressed in RB1-deficient breast cancers." (PMID 28977935, 2017). "Hence, RB1 loss, a common event in breast cancer, results in increased mRNA levels of E2F1 target genes." (PMID 28977935, 2017). "Interestingly, a lot of rarely mutated putative driver genes that were detected in breast cancer have been described as copy number amplifications (e.g. ERBB2) or deletions (e.g. RB1, MEN1, PTEN) before." (PMID 25903787, 2015). "However, the ectopic expression of a mutated form of RB1, which was unable to induce growth arrest, protected RB1 deficient osteosarcoma and breast cancer cells from DNA damage-induced apoptosis." (PMID 26160835, 2015). "Indeed, the importance of overcoming this pRb-mediated proliferative barrier during cancer progression is supported by the high incidence of RB1 loss or mutations in human breast cancers with inactivated BRCA1 (refs 51, 52, 53)." (PMID 26106036, 2015). "Loss of RUNX1 may contribute to the development ofER+ luminal breast cancer under a background of eitherTP53 or RB1 loss and upon cooperation with otheradditional oncogenic events." (PMID 25415051, 2014). "We report for the first time point mutations affecting RB1 in breast cancer tissue." (PMID 20594292, 2010). "This is the first study reporting point mutations affecting RB1 in breast cancer tissue." (PMID 20594292, 2010). "In summary, we demonstrate for the first time point mutations in RB1 among breast cancer tumors." (PMID 20594292, 2010). "The present work is the first study reporting RB1 point mutations in primary breast carcinomas." (PMID 20594292, 2010). "Also present in this list was RB1CC1, a regulator of RB1 expression that has been shown to contain truncating mutations in breast cancers." (PMID 18782450, 2008). "We considered the possibility that there may be an excess risk of breast cancer in mothers in both groups, during early years of follow-up, mediated by mutations in the RB1 gene." (PMID 22275959, 2008). "The loss of the retinoblastoma tumour suppressor encoded by the RB1 locus is a well-characterised occurrence in many tumour types; however, its role in breast cancer is less clear with many reports demonstrating a loss of heterozygosity that does not correlate with a loss of RB1 protein expression." (PMID 18782450, 2008). "Similarly, the presence of ABCB10 and NUP133, and candidate tumor suppressors LRRFIP1 and RNU3IP2 in the RB1-related cluster, further support their functional association in breast cancer." (PMID 17280605, 2007). "The purpose of this study was to determine whether common variants in the RB1 gene are associated with breast cancer risk." (PMID 16685266, 2006). "Common variants in RB1 are therefore candidate for low to moderate risk breast cancer alleles." (PMID 16685266, 2006). "This observed fraction of RBness breast cancers raises an interesting question as to what fraction of the RBness population could be explained by obvious genomic or proteomic alterations in the RB1 gene/protein and what fraction might have a different cause of RBness." (PMID 40138429, 2025). "Consequently, the dysregulation of ATM and RB1 might be a crucial factor underlying the resistance of HER2-positive breast cancer cells to trastuzumab." (PMID 39655080, 2024).